RTL8A (retrotransposon Gag like 8A)
Synonyms: CXX1B; FAM127B; MAR8A; DKFZP564B147; SIRH6
Tractability: PROTAC: ubiquitination databases record sites on it.
Gene: Protein-coding gene on chromosome X (135,050,932 to 135,052,196, reverse strand). Ensembl gene ENSG00000203950.
Gene Ontology:
Molecular function: protein binding
Homologues: Orthologues: mouse Rtl8a (70% identical), mouse Rtl8b (70% identical), rat Rtl8a (70% identical), mouse Rtl8c (63% identical). Paralogues in human: RTL8B (96% identical), RTL8C (94% identical), LDOC1 (56% identical), RTL6 (36% identical), RTL3 (33% identical), PEG10 (32% identical), RTL5 (31% identical), RTL1 (30% identical), RTL10 (28% identical), RTL4 (11% identical).
Diseases named in the same sentence as RTL8A in open-access papers:
RTL8A is named in the same sentence as 4 diseases in open-access papers, as found by Europe PMC text mining. Sharing a sentence is not in itself a finding about the gene and the disease. The quoted sentences say what the papers report.
amyotrophic lateral sclerosis (1 paper, 2025). Amyotrophic lateral sclerosis (ALS) is a neurodegenerative disease characterized by progressive muscular paralysis reflecting degeneration of motor neurons in the primary motor cortex, corticospinal tracts, brainstem and spinal cord. "The biological roles of RTL8A, 8B and 8C (aka SIRH5, 6 and 4) remain unknown, although their involvement has recently been implicated in two human diseases, Angelman syndrome (AS) and amyotrophic lateral sclerosis (ALS)." (PMID 39875098, 2025).
RTL8A also shares sentences with these, for which no sentence is quoted: breast carcinoma (1 paper); colon adenocarcinoma (1); neurodegenerative disease (1).